TNF (tumor necrosis factor)
Diseases named in the same sentence as TNF in open-access papers (continued):
Sharing a sentence is not in itself a finding about the gene and the disease.
Cerebral ischemia (continued). "During cerebral ischemia, proinflammatory mediators such as TNF-α, IL-1β, and IL-6 are excessively produced by a variety of activated cell types, including microglia, endothelial cells, astrocytes, and neuron cells, which finally exacerbated neuronal injury." (PMID 27123035, 2016). "Cerebral ischemia activates astrocytes to release various pro-inflammatory cytokines, such as tumor necrosis factor-alpha (TNF-α) and interleukin-1β (IL-1β), which are crucial for the pathological processes of brain ischemic injury." (PMID 27724964, 2016). "In our study, we found a significantly increase of TNF-α concentration in the lung tissue after brain ischemia." (PMID 26931747, 2016). "Brain ischemia induces damage to astrocytes and stimulates the release of pro-inflammatory cytokines, such as tumor necrosis factor-α (TNF-α) and interleukin-1β (IL-1β), which are crucial for the pathological processes of brain ischemic injury." (PMID 26961366, 2016). "While in brain ischemia group, intensity of staining in typeIand II epithelial cells were both increased, a stronger dyeing of TNF-α was observed in alveolar type I and type II epithelial cells." (PMID 26931747, 2016). "ISH indicated that TNF-α was mainly located in macrophagocytes, which were significantly increased in the brain ischemia group." (PMID 26931747, 2016). "Tumor necrosis factor-α (TNF-α) is a proinflammatory protein produced in the brain in response to cerebral ischemia that promotes apoptosis." (PMID 26665003, 2015). "These in vitro neuroprotective effects were reaffirmed in an animal model of cerebral ischemia where 6-paradol showed therapeutic benefits by reducing microglial activation and TNF-α expression." (PMID 25789481, 2015). "Studies have indicated that TNF-α not only is related to the inflammations after cerebral ischemia, but also plays a role in the formation of thrombosis." (PMID 26609318, 2015). "It is involved in the regulation of inflammation and its activation is correlated with significant increases in levels of IL-1β and TNF-α following cerebral ischemia-reperfusion." (PMID 25815894, 2015). "During brain ischemia, proinflammatory cytokines such as TNF-α, IL-1β, IL-6, and chemokines such as CINC and MCP-1 are produced by a variety of activated cell types, including endothelial cells, microglia, astrocytes, and neurons." (PMID 25888869, 2015). "Expressed within the first hour after ischemic onset, TNF-α is also an essential component involved in the early stage of cerebral ischemia." (PMID 24877133, 2014). "Cerebral ischemia/reperfusion leads to release of pro-inflammatory mediators (TNF-α and IL-6) which in turns leads to production of MMP by resident and infiltrating cells, which altogether increase BBB permeability." (PMID 24465746, 2014). "In an anesthetized rat model of heatstroke, CD34+ cell therapy significantly attenuates arterial hypotension, intracranial hypertension, cerebral ischemia, hypoxia, and injury, and TNF-α overproduction during heatstroke." (PMID 24804231, 2014). "These actions of TNF-α and IL-1β providea central role in leukocyte infiltration and tissue injury after cerebral ischemia." (PMID 24946684, 2014). "Considering our and previous findings, we suggest that S100B/RAGE upregulates iNOS and TNF-α expression through p38 MAP kinase-induced NF-κB activation in the ischemic cortical penumbra during the subacute phase of mild cerebral ischemia." (PMID 24626220, 2014). "High levels of TNF-α in plasma also correlate also with infarct volume and neurological function in models of cerebral ischemia." (PMID 25086655, 2014). "Induction of cerebral ischemia increased the TNF-α, IL-6 and IL-1β mRNA expression levels significantly at 4 and 24 h in the left ischemic hemispheres in the hypoxia group compared with those in the control group." (PMID 24520277, 2014). "TNF-α also has been shown to be upregulated after cerebral ischemia with similar expression patterns as IL-1β." (PMID 25424430, 2014).
Cerebral ischemia (continued). "Activated microglial cells are the major producers of soluble TNF-α within the first 6 hours after cerebral ischemia." (PMID 25416145, 2014). "This protection has been mimicked in cell culture models of neuronal insult and animal models of brain ischemia with TNFα exposure prior to a damaging stimulus." (PMID 25407441, 2014). "In our animal models of brain ischemia, TNF-α increased over time in both ES and pMCAO, although they were higher in ES." (PMID 25086655, 2014). "For example, activated microglia following cerebral ischemia express a variety of proinflammatory cytokines including interleukin-1β (IL-1β), interleukin-6 (IL-6) and tumor necrosis factor-α (TNF-α), which induce neuroinflammation and neurotoxicity." (PMID 23912236, 2013). "TNF-α is an inflammatory factor that can be released by glial cells upon cerebral ischemia, and can induce ischemic injury." (PMID 24392007, 2013). "The TBI-induced cerebral ischemia, neurological motor deficits, and increased numbers of microglia-TNF-α double positive cells and increased TNF-α levels in the injured brain were all significantly attenuated by etanercept therapy." (PMID 23496862, 2013). "Maddahi and Edvinsson demonstrated that U0126 significantly inhibits the iNOS, IL-6, and TNF-α secretion in rat model of cerebral ischemia." (PMID 23671886, 2013). "Higher brain TNF levels have been reported in rats as compared to mice in equivalent severity of cerebral ischemia, so different responses between rodents and humans must be also expected." (PMID 23459929, 2013). "First, it has been reported that cerebral ischemia also induces activation of astrocytes, another resident cells in the brain, which can produce the proinflammatory cytokines including TNF-α, IL-1β and IL-6." (PMID 24349350, 2013). "We have further shown that the injurious effect of eNAMPT on cerebral ischemia was mediated by TNF-α released from glial cells." (PMID 24392007, 2013). "It was found that the expression of TNF-α gradually increases in cerebral ischemia at 1 h reperfusion following cerebral ischemia." (PMID 23864765, 2013). "In the earliest phase of cerebral ischemia, TNF-α is released predominantly from microglia, and plays a critical role in subsequent I/R-induced injury." (PMID 23972823, 2013). "Inflammation plays a crucial role in the pathophysiology of cerebral ischemia by producing inflammatory mediators, such as IL-1β, TNF-α, PGE2, NO, COX-2, and iNOS, which are important mediators implicated in the pathology of the ischemic brain." (PMID 23762140, 2013). "TNF-α is another inflammatory cytokine participating in the pathological process of cerebral ischemia/reperfusion." (PMID 23864765, 2013). "Another group reported that DEX protected nerve tissue from reperfusion-induced injury after -erm brain ischemia via reduced levels of TNF-α and decreased numbers of degenerative neurons in the hippocampus and dentate gyrus." (PMID 23840096, 2013). "It is suggested that the protective effect of GZFLC on rat brain ischemia-reperfusion injury is partly due to its inhibition of proinflammatory cytokines IL-1β and TNFα and upregulated expressions of anti-inflammatory cytokines IL-10." (PMID 23818926, 2013). "It was also shown that after MCAO mice deficient in TNF or functional CD95L, which belongs to the tumor necrosis factor (TNF) protein family, are protected against brain ischemia having reduced neuronal death and smaller degree of locomotor impairment." (PMID 23533818, 2013). "In contrast to those findings, administering TNF-α before cerebral ischemia is neuroprotective, and ischemic pre-conditioning increases levels of TNF-α to activate the neuroprotective functions behind Nf-κB." (PMID 22348126, 2012). "Activation of microglia and astrocytes leading to release of cytotoxic substances such as nitric oxide and TNFα have been reported in response to early brain injury after cerebral ischemia." (PMID 23259581, 2012).
Cerebral ischemia (continued). "Cytokines induced by cerebral ischemia such as TNF-α and granulocyte colony-stimulating factor also increase cIAP2 protein levels and thus enhance the apoptotic resistance of vascular endothelial cells and neurons." (PMID 23251498, 2012). "The proinflammatory cytokines TNFα, IL-6 and IL-1β have been found in the brain infarct region and the same cytokines have been suggested to be involved in the development of late cerebral ischemia after SAH." (PMID 23259581, 2012). "GW0742 administration i.c.v. dose-dependently inhibited the increase of TNF-α, IL-1β, and IL-6 and the reduction of IL-10 in hippocampus of cerebral ischemia-reperfusion rat." (PMID 23056034, 2012). "Rcan1-4 mRNA expression in the same brain ischemia model was determined by real time qRT-PCR, together with the mRNA expression levels of the proinflammatory cytokines IL-1β, TNFα and interleukin 6 (IL-6) and the proinflammatory gene cyclo-oxygenase 2 (Cox-2)." (PMID 22397398, 2012). "TNF inhibition also reduced cerebral ischemia/reperfusion injury, decreased TBI induced neuronal damage, and ameliorated BBB dysfunction after closed head injury." (PMID 22034986, 2011). "TNF-α serves as a marker for activation of microglia and macrophages during cerebral ischemia and other inflammatory reactions and appears to mediate cell death." (PMID 22082476, 2011). "We therefore suggest that organ culture can be used as a method to study mechanisms involved in enhanced expression of TNF-α and its receptors in cerebral arteries that occur following cerebral ischemia." (PMID 21871121, 2011). "Our results show that cerebral ischemia (MCAO, SAH) and organ culture are associated with enhanced TNF-α, TNF-R1 and TNF-R2 protein levels in the wall of cerebral arteries." (PMID 21871121, 2011). "The present study shows that cerebral ischemia and organ culture induce expression of TNF-α and its receptors in the walls of cerebral arteries and that upregulation is transcriptionally regulated via the MEK/ERK pathway." (PMID 21871121, 2011). "NF-κB is activated by a number of factors that are present during cerebral ischemia, which include activated glutamate receptors, reactive oxygen species (ROS), TNF-α, and IL-1β." (PMID 22132330, 2011). "TNF-α is a well known cytokine involved in the inflammatory response elicited in the region of cerebral ischemia." (PMID 21810263, 2011). "Together, these studies highlight the vast detrimental effects of TNF-α on both glial and neuronal functioning during cerebral ischemia." (PMID 21810263, 2011). "Several investigators have suggested a role of the MAPK-MEK-ERK pathway in the regulation of TNF-α following cerebral ischemia." (PMID 21871121, 2011). "In early studies with TNF KO mice Mattson showed clearly that damage to neurons by focal cerebral ischemia and excitotoxic insults was enhanced in TNFR-KO mice, implicating TNF as a neuroprotectant in the brain." (PMID 21810263, 2011). "Overall there is convincing data supporting both detrimental and protective effects of TNF in brain ischemia." (PMID 21810263, 2011). "Our data suggest for the first time that the enhanced expression of iNOS, IL-1ß, IL-6 and TNF-α in cerebral ischemia is a transcription/translational event in brain vessels, and points to a way to modify their expression by MEK/ERK1/2 inhibition." (PMID 20187933, 2010). "Following cerebral ischemia/reperfusion, TNF-α levels are increased within two hours, followed by a peak in P-selectin expression at 6 hours and a later peak in E-selectin expression between 6 and 12 hours." (PMID 20122276, 2010). "We have here demonstrated yet another important mechanism involved in cerebral ischemia, neuroinflammation, and we have demonstrated that U0126 blocks enhanced cerebrovascular expression of iNOS, IL-1ß, IL-6 and TNF-α." (PMID 20187933, 2010). "The pro-inflammatory cytokine TNF-alpha has been previously reported to be upregulated during cerebral ischemia." (PMID 21124781, 2010).
Cerebral ischemia (continued). "Microglia are activated following in cerebral ischemia and express a variety of proinflammatory cytokines including interleukin -1β (IL-1β), interleukin -6 (IL-6) and tumor necrosis factor -α (TNF-α), which induce in neuroinflammation and neurotoxicity." (PMID 20668522, 2010). "Activated microglia and macrophages are major producers of soluble TNF-α within the first 6 hours after cerebral ischemia." (PMID 21040547, 2010). "In cerebral ischemia, TNF-α probably has a dual function: neurotoxicity via upregulation of inducible nitric oxide synthase, and neuroprotection in the absence of nitric oxide synthase." (PMID 19421412, 2009). "In this study, we also demonstrated that puerarin can downregulate the transcription of TNF-α during brain ischemia." (PMID 19272172, 2009). "Some of the therapeutic effect of antiplatelet agents in brain ischemia involves modulation of TNF–α." (PMID 19421412, 2009). "In this paper, we describe the first application of focal cerebral ischemia in a unique transgenic rat overexpressing the murine TNFα gene." (PMID 18947406, 2008). "In animal models of cerebral ischemia, high levels of TNFα have been found after global and focal ischemic injury." (PMID 18947406, 2008). "Istradefylline significantly attenuated the elevation of microglia and astrocyte pro-inflammatory markers (inducible nitric oxide synthase (iNOS) and tumor necrosis factor-alpha (TNF-α)) as well as the neuronal NOS (nNOS) following cerebral ischemia induced by PVD surgery." (PMID 40565142, 2025). "Therefore, inhibiting the release of IL1β, IL6, and TNFα can effectively reduce neuron apoptosis, improve neurological deficits, reduce the disability rate and improve the quality of life of patients with cerebral ischemia." (PMID 41154631, 2025). "Following cerebral ischemia, immune cells, including microglia, undergo activation, transitioning from the M2 to the M1 phenotype, which leads to the production of pro-inflammatory cytokines such as IL-1β, IL-6, TNF-α, and chemokines." (PMID 40365317, 2025). "A single dose of LGU (0.72, 2.16 mg/kg) could significantly reduce the contents of TNF-α and IL-1β in the infarction-side brain tissue of the cerebral ischemia/reperfusion injury model." (PMID 38927572, 2024). "Notably, SITG has reduced pro-inflammatory markers NF-κB, TNF-α, and IL-6 in diabetic rats with cerebral ischemia/reperfusion injury." (PMID 39766390, 2024). "An animal experiment illustrated that anti-CD147 antibody could inhibit the inflammatory response of monocyte/macrophage in the spleen after cerebral ischemia in mice and reduce the levels of TNF-α, IL-6 and IL-1β in the spleen." (PMID 38932932, 2024). "Cerebral ischemia induces astrocytes to release inflammatory factors, such as IL-1, IL-6, and TNF-α, and neurotoxins that may kill matured oligodendrocytes or inhibit the maturation of oligodendrocyte precursor cells." (PMID 38464836, 2024). "Previous studies showed that allicin could reduce cerebral infarction areas, neuronal apoptosis, myeloperoxidase (MPO) activity, and tumor necrosis factor (TNF)‐α levels in serum to protect the brain from cerebral ischemia/reperfusion injury." (PMID 37673878, 2023). "In our study, the results demonstrated that the number of TUNEL-positive cells, Bax, cleaved caspase-3, cleaved caspase-9, PARP, IL-1β, IL-6 and TNF-α protein expression were enhanced after cerebral ischemia‒reperfusion injury, while antiapoptotic Bcl-2 protein expression was decreased." (PMID 37248543, 2023). "By inhibiting JAK2/STAT3 signaling pathway, curcumin reduces the expression of HMGB1 in brain tissue after cerebral ischemia and reduces the release of TNF‐α and other inflammatory factors after cerebral ischemia, which significantly reduce the inflammatory response after cerebral ischemia." (PMID 38156383, 2023).
Cerebral ischemia (continued). "Tanshinone IIA can reduce the expression of macrophage migration inhibitory factor (MIF) and inflammatory factors (MIF), TNF-α and interleukin (IL)-6 in the brain of rats with cerebral ischemia/reperfusion, thereby alleviating the effects of cerebral ischemia/reperfusion." (PMID 37808475, 2023). "Furthermore, IL-1β, IL-6 and TNF-α mRNA levels were enhanced after cerebral ischemia‒reperfusion injury, consistent with previous reports." (PMID 37248543, 2023). "The expression of TNF-α is rapidly upregulated after cerebral ischemia, leading to neurotoxicity." (PMID 36970418, 2023). "During cerebral ischemia, statins also inhibit the expression of inflammatory cytokines, TNFα and Interleukin-6 (IL-6), in vascular endothelial cells to prevent BBB disruption, and at the site of BBB disruption, they act directly on brain nerve cells to exert their effects." (PMID 36852215, 2023). "After brain ischemia, astrocytes are stimulated and induce the production of many inflammatory mediators, including the transcription factor NF-KB, tumor necrosis factor (TNF), interleukins (IL), and interferons (IFN)." (PMID 37256231, 2023). "Our results reveal that TLR3, NF‐κB, and TNF‐α could be utilized as predictive biomarkers for poly I:C treatment against cerebral ischemia injury." (PMID 35510663, 2022). "Therefore, restraining the abnormal activation of A1 astrocytes and production of TNF-α and IL-6 is conducive to alleviating neuronal damage after cerebral ischemia, which is also indispensable for functional rehabilitation." (PMID 35559267, 2022). "The regulatory effect of HG on macrophage polarization is supported by a previous study showed that HG significantly reduced M1 pro-inflammatory microglia and decreased the levels of TNF-α and IL-6 within the infarcted areas to alleviate cerebral ischemia/reperfusion injury [PMID: 32,848,779]." (PMID 35266443, 2022). "Moreover, the TNF signaling pathway, the fifth signaling pathway, retracted inflammatory response after cerebral ischemia–reperfusion injury." (PMID 35873563, 2022). "Also, SAL has been shown to exert anti-inflammatory effect and prevent brain edoema by reducing the expression of TNF-α and neutrophil infiltration in rats with cerebral ischemia-reperfusion injury." (PMID 36086879, 2022). "A number of reports point to the damaging role of TNFα activated by brain ischemia." (PMID 35955430, 2022). "Some studies have found that cytokines such as TNF-α, IL-1α/β and IL-6 affect phospholipid metabolism during acute inflammatory reaction under cerebral ischemia, producing arachidonic acid-like substances, ceramides and reactive oxygen species (ROS), which can cause damage to the brain tissue." (PMID 34504432, 2021). "In addition, D. moldavica has been reported to markedly improve on rat cerebral ischemia reperfusion injury by reducing the levels of IL-6, IL-8 and TNF-α and elevating the activities of superoxide dismutase (SOD) and glutathione peroxidase (GSH-Px)." (PMID 34960054, 2021). "More and more studies have shown that a variety of inflammatory cytokines, such as TNF-α, IL-1β, and IL-6, are released after cerebral ischemia, which can transform ischemic injury into inflammatory injury and promote the apoptosis and necrosis of nerve cells and the formation of brain edema." (PMID 34447315, 2021). "Experiments had shown that an increase in the amount of TNF-α could promote the inflammatory response after cerebral ischemia/reperfusion (CI/R) and aggravated brain damage, while TNF-α inhibitors could reduce CI/R injury." (PMID 34582494, 2021). "Relationships between peripheral proinflammatory cytokine levels and infarct size following cerebral ischemia have been reported in the literature for some time with hints that TNFα may have a privileged status with respect to influencing brain integrity." (PMID 34067023, 2021).